RNU1-11P (RNA, U1 small nuclear 11, pseudogene)
Synonyms: U1P1A; RNU1P1; formerly RNU1P5
Gene: Small nuclear RNA gene on chromosome 6 (13,214,056 to 13,214,219, forward strand). Ensembl gene ENSG00000206702.
Homologues: Orthologues: chimpanzee U1 (99% identical), rabbit U1 (95% identical). Paralogues in human: RNU1-1 (96% identical), RNU1-2 (96% identical), RNU1-27P (96% identical), RNU1-28P (96% identical), RNU1-3 (96% identical), RNU1-4 (96% identical), RNVU1-18 (96% identical), RNVU1-29 (96% identical), U1 (96% identical), RNVU1-28 (95% identical), RNVU1-7 (95% identical), RNVU1-31 (95% identical), and 134 more.